ATAD2 (ATPase family AAA domain containing 2)
Diseases named in the same sentence as ATAD2 in open-access papers (continued):
Sharing a sentence is not in itself a finding about the gene and the disease.
cancer (81 papers, 2011 to 2026). A tumor composed of atypical neoplastic, often pleomorphic cells that invade other tissues. "Evasion of apoptosis is a hallmark of cancer, and previous studies have shown that ATAD2 plays a critical role in promoting anti-apoptotic activity in cancer cells." (PMID 41154392, 2025). "ATAD2 levels are low or absent in healthy somatic cells, but ATAD2 is upregulated in diverse cancer types, wherein high ATAD2 expression is associated with a high histological grade, high rates of metastasis and recurrence, and poor overall survival." (PMID 39335162, 2024). "For instance, ATAD2 deficiency impedes cancer cell proliferation and induces apoptosis through inhibition of the MAPK and PI3K-AKT pathways." (PMID 39201586, 2024). "As the oncogenic effects are closely related to pathogenesis, ATAD2 has emerged as a diagnostic and prognostic marker in numerous malignant tumors, and has attracted attention as a drug target for the inhibition of cancer progression." (PMID 37922300, 2023). "Studies have shown that the loss of ATAD2 results in decreased protein expression of EMT to impede cancer cell migration and invasion." (PMID 36632213, 2023). "ATPase family AAA domain-containing protein 2 (ATAD2) has been emerging as a hot anti-cancer drugable target due to its oncogenic epigenetic modification closely associated with cancer cells proliferation, apoptosis, migration and drug resistance." (PMID 37533352, 2023). "ATPase family AAA domain-containing protein 2 (ATAD2) has been widely reported to be a new emerging oncogene that is closely associated with epigenetic modifications in human cancers." (PMID 36632213, 2023). "Among all tested BrD proteins, the newly discovered positive association between ATAD2 and cancer de‐differentiation status emerges as universal regardless of the tumor type." (PMID 35049055, 2022). "Specifically, our approach allowed us to discover a robust association of high ATAD2 expression with cancer stemness and reveal its' versatility in tumors." (PMID 35049055, 2022). "In summary, we identified miR-302 as a novel miRNA that suppresses cancer cell behaviors associated with tumor progression by directly targeting ATAD2." (PMID 36139505, 2022). "Here, using the TCGA and GEO transcriptomic data, we report yet unrecognized association between ATAD2 overexpression and cancer stemness in solid tumors across distinct tumor types." (PMID 35049055, 2022). "For example, the gene encoding the ATAD2 AAA-ATPase bromodomain-containing protein has emerged as a possible therapeutic target in cancer." (PMID 34298819, 2021). "ATAD2 is an ATPase that is overexpressed in a variety of cancers and associated with a poor patient prognosis." (PMID 29469144, 2018). "Increased expression of the ATAD2 gene has been implicated in cancer development and progression in a number of tissues, but few studies have investigated ATAD2 expression using IHC." (PMID 26308378, 2015). "The association between dependency on MYC and ATAD2 suggests ATAD2 as a therapeutic target in MYC-dependent cancers." (PMID 23393560, 2013). "Also, ATAD2-related transcriptome profiles were significantly enriched with known stem cell-derived gene signatures and “cancer hallmark” terms specific for stemness-high tumors, especially the activation of E2F and c-Myc-dependent transcription." (PMID 36674511, 2023). "ATAD2 is involved in the activation of multiple oncogenic signaling pathways and is closely associated with tumorigenesis, progression, chemoresistance, and poor prognosis, but the oncogenic mechanisms vary in different cancer types." (PMID 36008934, 2022). "Further GSEA analyses with MSigDB Hallmark (v7.4) gene sets as a reference confirmed robust enrichment of ATAD2‐associated transcriptome profiles with “cancer hallmark” terms specific for stemness‐high tumors, especially the activation of c‐Myc‐dependent transcription." (PMID 35049055, 2022).
cancer (continued). "Studies show that the subclass IV ATAD2 is a generalist facilitator of chromatin dynamics in embryonic stem cells, and that bromodomain mutations can disable ATAD2’s ability of promoting cancer cell proliferation." (PMID 29077715, 2017). "Hence our work provides an explanation why high levels of ATAD2 are associated with poor prognosis of patients in various cancers." (PMID 27612420, 2016). "We also investigated whether 8q24 amplification is associated with increased ATAD2 expression in other cancer types." (PMID 23393560, 2013). "However, gain-of-function of TCF19 and ATAD2 is associated with cell proliferation in cancer." (PMID 40962957, 2025). "Thus, due to its important role in DNA replication and DDR, ATAD2 may be a potential candidate target in cancers that are susceptible to DNA damage." (PMID 36632213, 2023). "Given the growing evidence that ATPase family AAA domain containing 2 (ATAD2) is implicated in various cancers and might be a marker of poor prognosis, chemical probes and inhibitors targeting this protein are gradually attracting the attention of investigators." (PMID 37142850, 2023). "Besides, ATAD2 overexpression was significantly associated with poorer overall survival, relapse-free survival, disease-free survival, and disease-specific survival, suggesting an indicative role for ATAD2 in the prognostic significance of human cancers." (PMID 36632213, 2023). "The close association between ATAD2 and malignancies suggests that ATAD2 has multifaceted oncogenic effects and is not only an emerging biomarker for the diagnosis and prognosis of many malignant tumors but also a potential drug target for the therapy of malignancies." (PMID 36008934, 2022). "In addition, ATAD2 was also directly associated with AR to activate AR-mediated transcription and was required to regulate the expression of androgen-induced genes that controlled cancer cell proliferation and survival." (PMID 26697062, 2015). "Here, we showed that Atad2 is highly expressed in post-meiotic spermatogenic cells and that in its absence, as in ES cells and in different cancer cells, HIRA accumulates." (PMID 41557467, 2026). "Although ATAD2’s function in cancer prompted many investigations, its function in its physiological context of expression has remained largely overlooked." (PMID 41557467, 2026). "ATAD2 binds to c-Myc, enhancing the transcriptional activity of c-Myc on downstream targets and promoting aggressive cancer progression." (PMID 41158756, 2026). "There have been reports of various miRs that downregulate ATAD2’s expression, inhibiting cancer growth and progression." (PMID 41154392, 2025). "Given the significant function of ATAD2 in numerous cancers, the hunt for small-molecule inhibitors that target ATAD2 has been an increasingly prevalent subject in oncological research." (PMID 41154392, 2025). "Overall, we hope this review serves as a valuable reference for researchers, providing a foundation for future studies aimed at exploring ATAD2’s full therapeutic potential in cancer." (PMID 41154392, 2025). "This review provides a comprehensive overview of the structural features, functional roles, and biological significance of ATAD2, particularly in the context of cancer." (PMID 41154392, 2025). "This immune dysfunction represents a critical barrier to effective immunotherapy, underscoring ATAD2 as a key regulator of both drug resistance and immune evasion in cancer." (PMID 41154392, 2025). "Among them, ATPase family AAA domain-containing protein 2 (ATAD2), also known as AAA+ nuclear coregulator cancer-associated (ANCCA), has emerged as a significant target because of its important role in cancer." (PMID 41154392, 2025). "miR-372 has been shown to bind to the 3′ UTR section of ATAD2 and inhibit its expression, suppressing oncogenesis in cancers of the liver, ovaries, and kidneys." (PMID 41154392, 2025).
cancer (continued). "We detailed its biological activities with a particular focus on its role in cancer, highlighting how ATAD2 functions as a transcriptional co-regulator through interactions with acetylated histones and key transcription factors." (PMID 41154392, 2025). "In cancer cells, overexpressed ATAD2 interacts with a range of transcription factors and chromatin-modifying proteins to stimulate gene expression, which prevents apoptosis and promotes cell proliferation." (PMID 41154392, 2025). "Despite rising evidence of ATAD2’s role in carcinogenesis, further research is needed to determine its precise actions across different cancer types." (PMID 41154392, 2025). "This review provides a comprehensive overview of ATAD2, including its structure, biological functions, and role in cancer progression." (PMID 41154392, 2025). "ATPase family AAA domain-containing protein 2 (ATAD2) has been recognized as a key oncogene that regulates chromatin remodeling, transcription, and cancer progression." (PMID 41154392, 2025). "Conversely, forced ATAD2 expression can restore cell cycle progression and enhance chemosensitivity in hypoxic cancer cells." (PMID 41154392, 2025). "In cancer biology, extensive crosstalk, overlapping nodes, and forward–backward feedback loops are common, and ATAD2 functions as part of this interconnected network." (PMID 41154392, 2025). "In this complex landscape, the precise biochemical functions of ATAD2 in cancer pathology remain an area of ongoing and evolving research." (PMID 41154392, 2025). "Since histone acetylation regulates transcriptional programs that determine cellular responses to therapy, cancer cells exploit epigenetic mechanisms, including ATAD2-mediated chromatin modulation, to evade cytotoxic effects." (PMID 41154392, 2025). "Since ATAD2 controls the transcription of a specific collection of genes that activate the proliferative activity of cancer cells through a variety of pathways, it functions as a crucial transcription factor or coactivator in malignancies." (PMID 41154392, 2025). "The several cancer pathways ATAD2 regulates are explained in detail in this section, along with the molecular underpinnings that make ATAD2 a viable target in cancer." (PMID 41154392, 2025). "Together, these results suggest that the chemotherapy resistance of hypoxic cancer cells due to ATAD2 protein degradation is triggered by the inactivation of 2-OGDD and mediated by the proteasome pathway independent of HIFs and pVHL." (PMID 38730681, 2024). "Based on these results, we concluded that hypoxia induces chemotherapy resistance in cancer cells by decreasing the ATAD2 protein levels and delaying cell cycle progression, especially in the early S phase." (PMID 38730681, 2024). "Due to these functions, ATAD2 has garnered considerable attention in cancer research as a promising target for anticancer therapies and a potential biomarker across various malignant tumors." (PMID 39201586, 2024). "ATAD2, as an epigenetic bromodomain-containing oncology target overexpressed in many cancers, has attracted widespread attention among pharmaceutical companies." (PMID 36632213, 2023). "As an important epigenetic target, ATAD2 can regulate the expression of various cancer-related genes and participate in all aspects of cancer progression." (PMID 36632213, 2023). "In our previous review, ATAD2 plays an essential role in cancer chromatin remodelling, DNA replication, DNA damage, and DNA repair, and is associated with cancer cell proliferation, migration, autophagy, and cell cycle regulation." (PMID 37533352, 2023). "Due to its critical and extensive regulatory role, ATAD2 has emerged as a promising drug target for cancer treatment." (PMID 37533352, 2023). "Excitingly, ATAD2 has also been identified to be involved in the regulation of gonadal hormone signaling in cancer progression." (PMID 36632213, 2023).
cancer (continued). "Previously, we reported a consistent positive correlation of ATAD2 expression with cancer stemness across distinct tumor types." (PMID 36674511, 2023). "Excitingly, ATAD2 is also involved in regulating this complex network that governs the fate of cancer." (PMID 36632213, 2023). "To date, there are several reports implying ATAD2 involvement in mechanisms related to cancer stemness." (PMID 36674511, 2023). "Over-expressed ATAD2 interacts with various transcription factors and chromatin-modifying proteins in cancer cells and promotes tumor growth by inducing the full expression of genes that promote cell proliferation and inhibit cell apoptosis." (PMID 36632213, 2023). "Intriguingly, ATAD2 has also been found to contribute significantly to cancer response to hypoxia and EMT." (PMID 36632213, 2023). "Together, these inspiring findings would shed new light on ATAD2 as a promising druggable target in cancer and provide a clue on the development of candidate anticancer drugs." (PMID 36632213, 2023). "Accordingly, ATAD2 can encourage the process of cell cycle through a variety of aspects to promote cancer progression." (PMID 36632213, 2023). "Strikingly, abnormal cell cycle is also a major feature of cancer, and more and more evidence also shows that ATAD2 plays an important role in the regulation of various stages of cancer cell cycle." (PMID 36632213, 2023). "Undoubtedly, ATAD2 has an important hopeful targeting value in cancer therapy, and these biological processes regulated by ATAD2 are the molecular basis for ATAD2 to become a promising candidate drug target in cancer therapy." (PMID 36632213, 2023). "Recent studies have demonstrated that ATAD2 is overexpressed in several cancer types and plays a role in the regulation of key oncogenes, such as c-Μyc and E2F1, in genome regulation, cell proliferation, differentiation, and apoptosis." (PMID 37479754, 2023). "In this section, we mainly elaborate on the cancer pathways regulated by ATAD2 and further clarify the molecular basis of ATAD2 as a promising candidate cancer target." (PMID 36632213, 2023). "Based on these findings, new and potent small-molecule inhibitors targeting ATAD2 are currently being tested as therapeutic agents in various cancer types." (PMID 37479754, 2023). "As miRNAs regulating ATAD2 expression have been reported to suppress cancer proliferation and progression, we used mRNA targeting-prediction algorithms (TargetScan) to identify putative miRNAs targeting ATAD2." (PMID 36139505, 2022). "ATAD2 was discovered to be a key factor in the deregulation of the kinesin family (KIFs), and the dysregulation of kinesin promotes cancer growth." (PMID 36008934, 2022). "ATAD2 (ATPase family AAA structural domain-containing protein 2) is a cancer testicular protein involved in multiple signaling pathways." (PMID 36479043, 2022). "The pRB‐E2F pathway tightly regulates ATAD2 expression, which is essential for the growth of normal and cancer cells." (PMID 35049055, 2022). "Our results demonstrate that significant upregulation of ATAD2 and SMARCA4, and downregulation of SMARCA2 is consistently associated with enriched cancer stem cell‐like phenotype, respectively." (PMID 35049055, 2022). "Both the AAA ATPase and bromodomain are the most protected domains of ATAD2 and are also the main targets of cancer drug therapy research." (PMID 36008934, 2022). "Results obtained for FBXO32, ZHX1 and ANXA13 genes encoded within the same region as ATAD2 clearly emphasize the specificity of ATAD2 and MYC as well as ATAD2 and cancer stemness associations." (PMID 35049055, 2022). "ATAD2 is highly expressed in multiple cancers and plays multifaceted oncogenic functions in the proliferation and survival of cancer cells." (PMID 36139505, 2022). "We report yet unrecognized correlation between ATAD2 upregulation and significant enrichment of stem cell‐like phenotype in cancer and prove its' versatility across solid tumors." (PMID 35049055, 2022).
cancer (continued). "We have recently reported that the significant upregulation of the BrD family members ATAD2 and SMARCA4 and downregulation of SMARCA2 are associated with enriched cancer stemness." (PMID 36614001, 2022). "Our results demonstrated a new interaction transcription factor of ATAD2, providing important reference for exploring the molecular mechanism of ATAD2 in other cancer types." (PMID 33757572, 2021). "In invasive tumors, the overexpressed and amplified of ATAD2 has been reported, ATAD2 is mapped to chromosome 8q24.13, a genomic region frequently amplified in multiple cancer types,which is highly expressed in several different types of human tumors." (PMID 34112093, 2021). "Since ATAD2 overexpression is correlated with cancer development, several inhibitors have been developed to target the ATAD2 bromodomain." (PMID 34298819, 2021). "Our parallel studies of ATAD2’s function in distinct models, S. pombe, human cancer cells and mouse ES cells, consistently support that ATAD2 is a critical regulator of histone deposition by FACT and HIRA." (PMID 34580178, 2021). "The human homolog of Yta7, ATAD2 is an emerging oncogene and overexpressed in various cancers with poor prognosis." (PMID 34471130, 2021). "Yta7 is conserved among eukaryotes with its human homolog ATAD2 emerging as an oncogene overexpressed in various cancers with poor prognosis." (PMID 34471130, 2021). "As a unique member of BRD family, the function and molecular mechanism of ATAD2 in cancer development is seldomly investigated." (PMID 33757572, 2021). "Almost all of our current knowledge regarding the functions of ATAD2 derives from various cancer-related studies, which suggest a general role for ATAD2 as a pro-oncogenic factor stimulating oncogenic transcription factor activity and cell growth." (PMID 34580178, 2021). "In human cancer cell lines and in mouse embryonic stem cells, we observed that the KO of ATAD2 leads to an accumulation of HIRA." (PMID 34580178, 2021). "qRT-PCR analysis detected significantly higher ATAD2 mRNA expression in cancer than normal tissues in 73 out of 83 paired tissues." (PMID 33757572, 2021). "The important function of ATAD2 in cancer attracts deep insight into the structure of ATAD2, and surprisingly, the bromodomain of ATAD2 has been validated to be a pharmacologically tractable target and a series of inhibitors are disclosing." (PMID 33757572, 2021). "ATAD2 is overexpressed in multiple types of cancer including breast, lung, gastric, endometrial, colorectal, renal, and prostate, and overexpression of ATAD2 is often correlated with poor patient outcomes, and can be used as prognostic marker." (PMID 34298819, 2021). "Targeting ATAD2 represents a promising method for the development of therapeutic treatments for cancer." (PMID 32462022, 2020). "The overexpression of ATAD2 was correlated with race (P = 0.008), a family history of cancer (P = 0.018), and tumor grade (P < 0.001)." (PMID 32462022, 2020). "ATAD2 is a valid and promising therapeutic target involved in cell survival, proliferation, apoptosis, and migration for several types of human cancers." (PMID 32174193, 2020). "Abo1 and ATAD2 can thus be added to a range of chromatin-interacting proteins of relevance in cancer biology, yet little is known about their function in mechanistic terms." (PMID 32191554, 2020). "This score revealed ERGs with a high Multi-Omics Driver score in most cancer types (such as ATAD2) against those showing single driver score (such as IDH1, which has a high SNA driver score in LGG but relatively low CNA and expression driver scores)." (PMID 32963031, 2020). "The TCGA dataset results indicated that a high level of ATAD2 expression was closely correlated with race, a family cancer history, tumor grade, and disease stage." (PMID 32462022, 2020). "S. pombe Abo1 is a highly conserved homologue of human ATAD2, which is an oncogene overexpressed in many cancers with poor prognosis." (PMID 32191554, 2020).